SERPINB8 (serpin family B member 8)
Description:
Has an important role in epithelial desmosome-mediated cell-cell adhesion.
Synonyms: CAP2; PI-8; PI8; C18orf53; PSS5
Tractability: PROTAC: ubiquitination databases record sites on it; its protein half-life has been measured.
Gene: Protein-coding gene on chromosome 18 (63,970,029 to 64,019,779, forward strand). Ensembl gene ENSG00000166401.
Subcellular location: Cytoplasm
Subcellular location (Human Protein Atlas): Actin filaments; Golgi apparatus; Cytosol
Pathways (Reactome):
Hemostasis: Dissolution of Fibrin Clot
Gene Ontology:
Molecular function: protein binding; serine-type endopeptidase inhibitor activity
Biological process: epithelial cell-cell adhesion; negative regulation of endopeptidase activity
Cellular component: cytosol; extracellular exosome; extracellular matrix; cytoplasm
Genetic constraint (gnomAD): Loss-of-function variants: 23 observed, 29.47 expected, observed/expected ratio (o/e) 0.78, 90% interval 0.56 to 1.11. The upper end of that interval is the gene's LOEUF score, 1.11, which puts it in group 4 of 6, group 1 being the genes least tolerant of losing a copy. Missense variants: 453 observed, 441.36 expected, observed/expected ratio (o/e) 1.03, 90% interval 0.95 to 1.11. Synonymous variants: 182 observed, 164.15 expected, observed/expected ratio (o/e) 1.11, 90% interval 0.98 to 1.25.
Homologues: Orthologues: chimpanzee SERPINB8 (99% identical), macaque SERPINB8 (97% identical), pig SERPINB8 (85% identical), dog SERPINB8 (83% identical), rabbit SERPINB8 (79% identical), mouse Serpinb8 (78% identical), guinea pig SERPINB8 (77% identical), rat Serpinb8 (71% identical), tropical clawed frog serpinb6 (57% identical), zebrafish serpinb14 (49% identical), zebrafish zgc:173729 (49% identical), zebrafish serpinb1l4 (49% identical), and 2 more. Paralogues in human: SERPINB6 (67% identical), SERPINB9 (63% identical), SERPINB1 (53% identical), SERPINB2 (47% identical), SERPINB10 (47% identical), SERPINB4 (46% identical), SERPINB3 (45% identical), SERPINB11 (44% identical), SERPINB12 (42% identical), SERPINB13 (41% identical), SERPINC1 (38% identical), SERPINB5 (37% identical), and 24 more.
Diseases named in the same sentence as SERPINB8 in open-access papers:
SERPINB8 is named in the same sentence as 21 diseases in open-access papers, as found by Europe PMC text mining. Sharing a sentence is not in itself a finding about the gene and the disease. The quoted sentences say what the papers report.
psoriasis (3 papers, 2012 to 2024). An autoimmune condition characterized by red, well-delineated plaques with silvery scales that are usually on the extensor surfaces and scalp. "AGT(SerpinA8) and SerpinB8 are susceptibility gene for psoriasis, but the specific mechanism has not been studied." (PMID 39737188, 2024). "SerpinB8 is a susceptibility gene for psoriasis, but the exact mechanism has not been studied." (PMID 39737188, 2024).
diabetes (2 papers, 2012 to 2021). "Within their gene families SERPINA6, SERPINB2, and SERPINB8 have long been known as biomarkers for diabetes." (PMID 34178943, 2021).
melanoma (2 papers, 2023 to 2025). A malignant, usually aggressive tumor composed of atypical, neoplastic melanocytes. "Some regulators (e.g., SERPINB8) have context-dependent roles: while it acts as a tumor promoter in melanoma, it functions as a suppressor in other cancers, raising concerns about off-target effects or conflicting biological roles in multi-tumor patients." (PMID 41008880, 2025). "SERPINB8 is correlated with high levels of T cell dysfunction in endometrial cancer and melanoma, as well as poor prognosis in melanoma, bladder cancer, and glioblastoma treated with ICB." (PMID 36588164, 2023). "Additionally, SERPINB9 (Serpin Family B Member 9) was recently reported to enhance resistance to ICB; SERPINB8 is a component gene of Overlap36 with unknown functions in melanoma." (PMID 36588164, 2023). "By using the TIDE (tumor immune dysfunction and exclusion) program, SERPINB8 predicts resistance to ICB in 14 of 25 cohorts at AUC values > 0.5, including NSCLC (AUC 0.68), melanoma (AUC 0.72), and gastric cancer (AUC 0.76)." (PMID 36588164, 2023). "In addition to melanoma, CYTH4, AOAH, DENND1C, TBC1D10C, EPSTI1, SERPINB8, and GIMAP7 stratify responders and non-responders to ICB in other cancer types." (PMID 36588164, 2023).
adenoma (1 paper, 2024). A neoplasm arising from the epithelium. "Top over-represented EV proteins from the adenoma ZMTH3 were mainly related to immune response (ISG15, BST2, IFI44), while top under-represented proteins identified in the adenoma ZMTH3 EVs were associated with migratory and adhesion activity (MXRA8, TNN, SERPINB8), similar to the WCLs." (PMID 39462388, 2024).
COVID-19 (1 paper, 2021). A disease caused by infection with severe acute respiratory syndrome coronavirus 2. "This suggests an important role for the miR-542-3p - SERPINB8 pathway for the pathogenesis of COVID-19 seen in the network." (PMID 34956213, 2021).
esophageal cancer (1 paper, 2021). A primary or metastatic malignant neoplasm involving the esophagus. "Patients with stage I esophageal cancer had significantly higher expression of CPS1 (p = 0.003), PNP (p = 0.007), SERPINB8 (p = 0.042) and EHD1 (p = 0.046)." (PMID 33828156, 2021).
Obesity (1 paper, 2013). Accumulation of substantial excess body fat. "Here we aimed to determine the role of serpinB8/furin in obesity-associated chronic inflammation." (PMID 23936445, 2013). "In conclusion, this study demonstrates upregulation of furin-like PCSKs (furin and PCSK5) for the first time and, furthermore, an imbalance of furin and its inhibitor serpinB8 in obesity." (PMID 23936445, 2013). "Because MCP-1 is the major chemoattractant derived from obese WAT, and resistin is abundantly found in circulating MNCs in obesity, regulation of furin, serpinB8 and MT1-MMP by these adipokines was compared." (PMID 23936445, 2013). "This study dissected the impact and interplay of the PCSK family member furin (PCSK3) and its inhibitor serpinB8 in WAT inflammation and obesity." (PMID 23936445, 2013). "Moreover, we examined the regulation of furin, serpinB8 and MT1-MMP in an animal model of obesity as well as in obese patients." (PMID 23936445, 2013). "However, the regulation and function of the natural furin-inhibitor serpinB8 and thus furin/MT1-MMP-activity in obesity-related tissue inflammation/remodeling is unknown." (PMID 23936445, 2013).
ovarian carcinoma (1 paper, 2014). A malignant neoplasm originating from the surface ovarian epithelium. "The other up-regulated genes in STOSE cells: Serpinb8, Epb41l4a, Aif1l, and Mgll have no known links to ovarian cancer." (PMID 24672774, 2014).
tumor (3 papers, 2020 to 2025). "Missense variants were found in MYPN, SERPINB8 (SPB8) and ESYT2, which were among the top ten most upregulated proteins in the tumour group." (PMID 33048956, 2020).
cancer (2 papers, 2023 to 2025). A tumor composed of atypical neoplastic, often pleomorphic cells that invade other tissues. "CYTH4, AOAH, DENND1C, TBC1D10C, EPSTI1, SERPINB8, and GIMAP7 are novel and robust individual genes in predicting resistance to ICB in multiple cancer types." (PMID 36588164, 2023).
bacterial infections (1 paper, 2022). "One of these proteins is protease inhibitor-serpin (SERPINB8), whose enhanced expression accompanies tick-saliva injection; but after the tick bite, its expression is induced mostly in bacterial infections and not in viral, due to the fact that its pro-survival action limits the spread of viruses." (PMID 35457192, 2022).
SERPINB8 also shares sentences with these, for which no sentence is quoted: bladder cancer (1 paper); clear cell renal cell carcinoma (1); Crohn disease (1); endometrial cancer (1); gastric cancer (1); glioblastoma (1); Immunodeficiency (1); schizophrenia (1); scleroderma (1); type 1 diabetes mellitus (1).